PCDH7 (protocadherin 7)
Diseases named in the same sentence as PCDH7 in open-access papers (continued):
Sharing a sentence is not in itself a finding about the gene and the disease.
cancer (continued). "Notably, the involvement of Pcdh7 in cell migration has been reported in cancer cell lines, including PC-3 and RPE1." (PMID 39859288, 2025). "PCDH7, a cell–cell adhesion regulator, emerges as a prognostic factor across cancers." (PMID 38167455, 2024). "In summary, PCDH7 has been considered an independent prognostic factor in various cancers." (PMID 38167455, 2024). "Approximately 20% of patients with Protocadherin 7 (PCDH7)-MN have malignant tumors." (PMID 38686366, 2024). "In other cancers, PCDH7 confers chemoresistance by inhibiting apoptosis and promoting anti-apoptotic protein expression and Wnt signaling, which could be targeted for GC treatment." (PMID 39456895, 2024). "The contradictory effects of PCDH7 in different cancer types suggest that PCDH7 might play different roles through different molecular mechanisms." (PMID 37063257, 2023). "PCDH7 has been reported to play a biological role in various cancer types." (PMID 37538171, 2023). "PCDH7 belongs to the cadherin superfamily and is involved in cancer stem cell oncogenesis." (PMID 36497225, 2022). "PCDH7, a member of the protocadherins family, acts as a tumor suppressor in various human cancers." (PMID 36311939, 2022). "It has been demonstrated that some cancer cells can selectively promote the assembly of gap junctions between cancer cells and astrocytes composed of connexin 43 (Cx43) by expressing protocadherin 7 (PCDH7)." (PMID 35046953, 2021). "However, they function differently in a specified context such as cancer cells, where PCDH7 attenuates cell-cell adhesion mediated by E-cadherin." (PMID 32457908, 2020). "PCDH7, a member of protocadherins family, functions as tumor suppressor in several human cancers." (PMID 27070091, 2016). "Recent studies suggested that PCDH7 functions as a tumor suppressor in human cancers." (PMID 27070091, 2016). "Furthermore, PCDH7 has multiple biological functions in various cancers." (PMID 37063257, 2023). "The expression of the PCDH7 gene, which was higher in HG-ESS than LG-ESS, was different in 14 cancer species." (PMID 38167455, 2024). "One study suggested that the expression of PCDH7 was related with lower metastasis-free survival in NSCLC patients and enhanced brain metastasis by facilitating the formation of carcinoma-astrocyte gap junctions." (PMID 36530971, 2022).
tumor (31 papers, 2011 to 2026). "CCL20, MMP14, and PCDH7 were upregulated in LUAD tumor tissues and linked to poor clinical outcomes, while BTG2, CD69, GPC3, IL7R, and NMUR1 are the opposite." (PMID 34881236, 2021). "Low PCDH7 immunoexpression has been associated with high pathological grade, recurrence, and tumor progression; this fact is an independent prognostic factor for clinical outcome and is associated with BC invasiveness." (PMID 33369468, 2020). "In conclusion, we reported for the first time that PCDH7 expression was decreased in NMIBC tissues and low PCDH7 expression was associated high pathologic grade, tumor recurrence and progression." (PMID 27070091, 2016). "Second, low PCDH7 expression was significantly associated with high grade, tumor recurrence and progression after curative surgery." (PMID 27070091, 2016). "Collectively, our results demonstrate that circDVL1 exerts tumor-suppressive function during ccRCC progression through circDVL1/miR-412-3p/PCDH7 axis, and suggest that circDVL1 could be a novel diagnostic and prognositc marker and therapeutic target for ccRCC." (PMID 35280687, 2022). "PCDH7 was expressed at a high level in stomach normal tissues and had diverse expression levels in GC tumor tissues, ranging from low expression and medium to high expression." (PMID 39606245, 2024). "Mouse-specific cells (vCM_mouse) also expressed higher levels of Pcdh7, calcium-dependent adhesion molecule, as well as Dlc1, a Rho GTPase activating protein with tumor suppressor function that is essential for embryonic development." (PMID 36401619, 2023). "Of these eight genes, four (GNAI3, PCDH7, PSEN1, TNFSF9) were highly expressed in tumor tissues and were associated with poor prognosis, while CD69, SLC11A2, and TLR2 were poorly expressed in tumor tissue and were associated with good prognosis." (PMID 36117156, 2022). "PCDH7 expression is dysregulated in tumorigenesis, with both oncogenic and tumor-suppressive activities reported in a context-dependent manner." (PMID 33963380, 2021). "The role of PCDHs in this group of neoplasms has been evaluated in fifteen studies, and the most re-searched are PCDH7, PCDH8, PCDH9, and PCH10." (PMID 33369468, 2020). "Together, we identified PCDH7 as the first trans-membrane protein that inhibits hoCIC formation to promote tumor growth." (PMID 32457908, 2020). "The results indicated that low PCDH7 expression correlated with advanced grade (P = 0.021) and larger tumor size (P = 0.044)." (PMID 27070091, 2016). "In EUR, we identified a significant effect of PCDH7, which may play a role in tumor development, on CanLU." (PMID 41044382, 2026). "In vivo experiments showed that PCDH7 knockdown cells formed a lighter tumor than control cells." (PMID 37538171, 2023). "Prior research unfolded that activated S100A4 signaling due to PCDH7-regulated tumor-astrocyte interaction could retain the self-renewal of TN-BCSCs and modulate their adaptation and colonization." (PMID 37838657, 2023). "Emerging evidence suggests that PCDH7 is aberrantly expressed in a variety of tumor types." (PMID 35280687, 2022). "Interestingly, functional rescue experiments revealed that the tumor suppressor properties of circDVL1 are partly due to its effect on PCDH7." (PMID 35280687, 2022). "In this study, we demonstrated that PCDH7 levels were reduced in ccRCC tumor specimens." (PMID 35280687, 2022). "Furthermore, PCDH7 expression induces the penetration of tumor cells over the blood-brain barrier, which then increases tumor cell intravasation in the brain." (PMID 33806911, 2021). "In GBM, miRNA-155HG was also correlated with poor prognosis, malignancy, EMT and tumor progression; these effects were the result of the modulation of miRNA-155 expression and its downstream target genes, such as protocadherin 7 and 9, both acting as tumor suppressors." (PMID 33328891, 2020).
tumor (continued). "A high PCDH7 level in the brain tropic CSC population has been reported and contributes to CSC extravasation, adaptation, and colonization in the new niche formation through the PCDH7-PLCb-Ca2þ-CaMKII/S100A4 pathway involving PCDH7-mediated tumor–astrocyte interaction." (PMID 32059676, 2020). "We demonstrate here that PCDH7 could significantly increase transformed tumor cell growth in anchorage-independent condition." (PMID 32457908, 2020). "Low PCDH7 expression correlated with advanced grade (P = 0.021) and larger tumor size (P = 0.044)." (PMID 27070091, 2016). "Therefore, PCDH7 may promote tumor growth via promoting cell proliferation, and inhibiting hoCIC formation as well." (PMID 32457908, 2020). "This stemness-associated signature integrates developmental drivers such as PTPRH, AHNAK2, PCDH7, metabolic regulators CPS1, SFTPB, and hypoxia-responsive factors such as TCN1, TMPRSS11E, reflecting the multifaceted nature of OSA-induced tumor evolution." (PMID 41584048, 2026). "We report the development and characterization of high-affinity anti-PCDH7 monoclonal antibodies (mAbs) that inhibit downstream mitogen-activated protein kinase (MAPK) pathway activation and suppress tumor growth in multiple mutant KRAS-driven models." (PMID 42234744, 2026). "Although S63845 alone only slightly inhibited tumor growth, it effectively enhanced the anti-cancerous role of ABT-263 under PCDH7 overexpression." (PMID 37063257, 2023). "The hot genes with the most positive signal events in the normal-specific group were RBPJ, PFKFB3, CAMK1D, ACACB, and WWOX, whereas the hot genes in the tumor-specific group were SLC35F3, PCDH7, NF1, and RAB27B." (PMID 36895481, 2023). "Differential analysis showed that GNAI3, PCDH7, PSEN1 and TNFSF9 were highly expressed in tumor tissues, while ADM, CD69, SLC11A2 and TLR2 were opposite." (PMID 36117156, 2022). "The expression of CCL20, CD70, PCDH7, DCBLD2, and MMP14 genes were remarkably more elevated within LUAD samples than adjacent non-tumorous tissues, where PIK3R5, RNF144B, BTG2, CD69, and MEP1A genes were the opposite." (PMID 36497225, 2022). "PCDH7 is a cell surface receptor protein that is highly expressed in NSCLC, inducing cell transformation and promoting tumor growth in vitro and in vivo." (PMID 36042374, 2022). "For five additional candidate targets including ITGA3 (n = 11), PCDH7 (n = 6), SLC39A10 (n = 6), ATP2B2 (n = 5), and HTR2B (n = 5), a quasi H − score ≥ 150 in at least 5 tumor types was also found." (PMID 33490264, 2021). "Intriguingly, facilitated by the connexin 43 protein (CX43) and protocadherin 7 (PCDH7), the cGAMP produced in tumor cells was exported to adjacent astrocytes via gap junctions." (PMID 32854711, 2020). "Functionally, PCDH7 silence inhibited ERK activation and tumor growths." (PMID 34580602, 2021). "Moreover, some non-clustered PCDHs have been suggested as candidate tumor suppressor genes in human tumors, including PCDH7, 8, 9 and 21 etc." (PMID 27070091, 2016).
PCDH7 also shares sentences with these, for which no sentence is quoted: neurodevelopmental disorder (3 papers); schizophrenia (2); Astigmatism (1); autism (1); autoimmune disease (1); central nervous system disorder (1); clear cell renal cell carcinoma (1); Down syndrome (1); focal epilepsy (1); generalized epilepsy (1); Hyperglycemia (1); Hypertension (1); Insulin resistance (1); juvenile myoclonic epilepsy (1); melanoma (1); neurological disorders (1); Obesity (1); oral cancer (1); portal hypertension (1); prostate tumors (1); renal carcinoma (1).